PSEN2 (presenilin 2)
Description:
Catalytic subunit of the gamma-secretase complex, an endoprotease complex that catalyzes the intramembrane cleavage of integral membrane proteins such as Notch receptors and APP (amyloid-beta precursor protein). Selectively cleaves late endosomal/lysosomal localized substrates and generates the prominent pool of intracellular amyloid beta that contains longer amyloid beta. The holoprotein functions as a calcium-leak channel that allows the passive movement of calcium from endoplasmic reticulum to cytosol and is involved in calcium homeostasis. Is a regulator of mitochondrion-endoplasmic reticulum membrane tethering and modulates calcium ions shuttling between ER and mitochondria.
Synonyms: PS-2; AD4; PS2; STM2; AD3L; E5-1; CMD1V
Tractability: Small molecule: a drug acting on it is in phase 2 or 3 trials; a structure with a bound ligand is known; a high-quality ligand is known; it belongs to a druggable protein family. Antibody: its Gene Ontology location is reachable by antibodies, with high confidence; UniProt predicts a signal peptide or a membrane-spanning region. PROTAC: ubiquitination databases record sites on it; a small molecule that binds it is known.
Target class: Presenilin ER Ca2+ leak channel family; Ion channel; Other ion channel; Miscellaneous ion channel
Gene: Protein-coding gene on chromosome 1 (226,870,184 to 226,927,726, forward strand). Ensembl gene ENSG00000143801.
Subcellular location: Endoplasmic reticulum membrane; Golgi apparatus membrane; Late endosome membrane; Lysosome membrane
Pathways (Reactome):
Signal Transduction: Activated NOTCH1 Transmits Signal to the Nucleus; NOTCH2 Activation and Transmission of Signal to the Nucleus; NOTCH3 Activation and Transmission of Signal to the Nucleus; NOTCH4 Activation and Transmission of Signal to the Nucleus; NRIF signals cell death from the nucleus; Noncanonical activation of NOTCH3; Nuclear signaling by ERBB4; Regulated proteolysis of p75NTR; TGFBR3 PTM regulation
Disease: Constitutive Signaling by NOTCH1 HD+PEST Domain Mutants; Constitutive Signaling by NOTCH1 PEST Domain Mutants
Developmental Biology: EPH-ephrin mediated repulsion of cells
Gene Ontology:
Molecular function: aspartic endopeptidase activity, intramembrane cleaving; protein binding
Biological process: amyloid precursor protein catabolic process; amyloid-beta formation; membrane protein ectodomain proteolysis; Notch receptor processing, ligand-dependent; protein processing; regulation of calcium import into the mitochondrion; calcium ion homeostasis; Notch receptor processing; Notch signaling pathway; intracellular signal transduction; response to hypoxia
Cellular component: centrosome; endoplasmic reticulum; endoplasmic reticulum membrane; gamma-secretase complex; Golgi apparatus; Golgi membrane; kinetochore; late endosome; late endosome membrane; lysosomal membrane; lysosome; membrane; nuclear inner membrane; plasma membrane; protein-containing complex; mitochondria-associated endoplasmic reticulum membrane contact site; early endosome; nuclear membrane; presynaptic membrane; synaptic membrane; synaptic vesicle
Genetic constraint (gnomAD): Loss-of-function variants: 32 observed, 50.54 expected, observed/expected ratio (o/e) 0.63, 90% interval 0.48 to 0.85. The upper end of that interval is the gene's LOEUF score, 0.85, which puts it in group 3 of 6, group 1 being the genes least tolerant of losing a copy. Missense variants: 522 observed, 614.62 expected, observed/expected ratio (o/e) 0.85, 90% interval 0.79 to 0.91. Synonymous variants: 255 observed, 256.63 expected, observed/expected ratio (o/e) 0.99, 90% interval 0.9 to 1.1.
Gene-disease validity (ClinGen):
ClinGen rates the evidence that PSEN2 causes each of these diseases.
dilated cardiomyopathy 1V (autosomal dominant): Limited.
Homologues: Orthologues: macaque PSEN2 (99% identical), pig PSEN2 (98% identical), dog PSEN2 (96% identical), mouse Psen2 (96% identical), guinea pig PSEN2 (96% identical), rat Psen2 (95% identical), rabbit PSEN2 (95% identical), chimpanzee PSEN2 (95% identical), tropical clawed frog psen2 (73% identical), zebrafish psen2 (70% identical), Drosophila melanogaster Psn (53% identical), Caenorhabditis elegans sel-12 (49% identical). Paralogues in human: PSEN1 (64% identical).
Diseases named in the same sentence as PSEN2 in open-access papers:
PSEN2 is named in the same sentence as 119 diseases in open-access papers, as found by Europe PMC text mining. Sharing a sentence is not in itself a finding about the gene and the disease. The quoted sentences say what the papers report.
Alzheimer disease (211 papers, 2005 to 2025). A progressive, neurodegenerative disease characterized by loss of function and death of nerve cells in several areas of the brain leading to loss of cognitive function such as memory and language. "Early-onset Alzheimer's disease (EOAD) is associated with highly penetrant mutations in genes such as PSEN2, whereas the strongest genetic risk factor for late-onset Alzheimer's disease (LOAD) is the APOE4 allele." (PMID 40959270, 2025). "Within a year of identifying PSEN1, another gene encoding the transmembrane protein PSEN2 was shown to have a substantial connection with Alzheimer’s disease." (PMID 40149496, 2025). "Mutations in the genes encoding APP, Presenilin-1 (PSEN1), and PSEN2 result in early-onset Alzheimer’s disease (AD)." (PMID 40783385, 2025). "Identification of pathogenic mutations in the PSEN2 gene in a Korean patient with early-onset Alzheimer’s disease emphasizes the significance of PSEN2 mutations." (PMID 41379817, 2025). "Rare genetic variants in the APP and PSEN1 and PSEN2 genes have been reported as pathogenic causes of early-onset Alzheimer’s disease, but they account for less than 1% of all cases." (PMID 39810256, 2025). "Well-known mutations in APP, PSEN1, and PSEN2 genes are primary causes of autosomal dominant early-onset Alzheimer’s disease (EOAD)." (PMID 41465142, 2025). "Alzheimer’s disease caused by PSEN2 mutations is extremely rare, and the age of onset is rather variable (45–88 years)." (PMID 38396302, 2024). "PSEN1 and PSEN2 mutations have been linked with the Amyloid protein precursor in early-onset Alzheimer disease." (PMID 38741048, 2024). "Mutations in presenilin 2 (PS2) have been causally linked to the development of inherited Alzheimer’s disease (AD)." (PMID 36766721, 2023). "Mutations in the APP, Presenilin 1 (PSEN1), and Presenilin 2 (PSEN2) genes are known to be a cause of early-onset forms of Alzheimer’s disease, termed familial Alzheimer’s disease (fAD)." (PMID 35013145, 2022). "Mutations in the genes for the amyloid-β precursor protein (APP) and the presenilins (PSEN1 and PSEN2) cause early-onset, dominantly inherited forms of Alzheimer’s disease (AD), whereas mutations in the MAPT gene mainly lead to frontotemporal dementia (FTD)." (PMID 35120450, 2022). "Mutations in the tau gene (MAPT) lead to frontotemporal dementia (FTD), whereas mutations in the genes for the amyloid-β precursor protein (APP) and the presenilins (PSEN1, PSEN2) cause early-onset, dominantly inherited forms of Alzheimer’s disease (AD)." (PMID 35120450, 2022). "Presenilin-2 (PSEN2) mutation Thr421Met was identified from a 57-years old patient with early onset Alzheimer's disease (EOAD) for the first time in Korea." (PMID 36362122, 2022). "Amyloid precursor protein (APP), presenilin 1 (PSEN1), and presenilin 2 (PSEN2) are associated with autosomal-dominant early-onset Alzheimer's disease (AD)." (PMID 36555832, 2022). "The established causative mutations in the APP, PSEN1, and PSEN2 can explain less than 1%,Alzheimer’s disease (AD) patients." (PMID 35491795, 2022). "PSEN2 gene is a protein-encoding gene with associated diseases such as Alzheimer’s disease and heart muscle diseases." (PMID 34306005, 2021). "Recent studies on post-ischemic brain neurodegeneration have revealed the dysregulation of Alzheimer's disease-associated genes such as amyloid protein precursor, α-secretase, β-secretase, presenilin 1, presenilin 2, and tau protein." (PMID 33679381, 2021). "Presenilin 2 is a transmembrane protein, initially isolated in a search for mutations associated with familial forms of Alzheimer’s disease." (PMID 34572962, 2021). "Less than 40 mutations in PSEN2 have been identified (Alzheimer Disease and Frontotemporal Dementia Mutation Database." (PMID 29599933, 2018). "Familial Alzheimer’s disease (AD) is predominantly caused by presenilin 1 (PSEN1) or presenilin 2 (PSEN2) mutations." (PMID 29875678, 2018).
Alzheimer disease (continued). "Impairment of γ-secretase carboxypeptidase activity, such as is caused by some familial Alzheimer’s disease mutations in APP or PSEN1 or PSEN2, can result in similar changes to the amyloid-β isoform ratios." (PMID 29945247, 2018). "It is known that dormant inherited mutations in APP, PSEN1, and PSEN2 lead to early onset Alzheimer’s disease (EOAD) and mutations in MAPT, GRN and C9ORF72 cause familial FTD." (PMID 30090657, 2018). "Mutations in the APP, PSEN1, and PSEN2 genes cause early onset Alzheimer’s disease (EOAD) that follows a Mendelian inheritance pattern." (PMID 29740579, 2018). "Dominantly inherited mutations in amyloid precursor protein (APP), presenilin 1 (PSEN1), and presenilin 2 (PSEN2) cause early-onset Alzheimer disease (AD)." (PMID 30045758, 2018). "Amyloid-β precursor protein (AβPP), presenilin 1 (PSEN1), and presenilin 2 (PSEN2) genes have been strongly implicated in early onset Alzheimer’s disease (EOAD), particularly familial EOAD, which comprise less than 5% of Alzheimer’s cases." (PMID 28373857, 2017). "Mutations in PSEN1 and PSEN2 are major causative genetic factors of familial cases of Alzheimer’s disease (AD), characterized by early onset AD manifestation." (PMID 29137240, 2017). "Amyloid protein precursor (APP), presenilin-1 (PSEN1), and presenilin-2 (PSEN2) mutations cause autosomal dominant forms of early-onset Alzheimer disease (AD-EOAD)." (PMID 28350801, 2017). "Some of these interesting genes, such as MAPT, CASP2, and PSEN2, are linked with important aspects of Alzheimer’s disease, such as dementia, increase cell death, and deposition of amyloid-beta proteins in Alzheimer’s disease brains." (PMID 27901073, 2016). "Mutations in three genes, amyloid precursor (APP), presenilin 1 (PSEN1) and presenilin 2 (PSEN2), play extremely important roles in the metabolism of Aβ, and these mutations have been identified as risk factors for Early Onset Alzheimer Disease (EOAD)." (PMID 24586483, 2014). "Missense mutations in three different genes encoding amyloid-β precursor protein, presenilin 1 and presenilin 2 are recognized to cause familial early-onset Alzheimer disease." (PMID 22044463, 2011). "While mutations in presenilin 1, presenilin 2 and β-amyloid precursor protein gene are highly penetrant causes of early-onset Alzheimer’s disease, these together account for less than 1 per cent of cases of Alzheimer’s disease in the general population." (PMID 21150010, 2010). "Approximately, 150 mutations in human PSEN1 and ten mutations in human PSEN2 have been associated with early onset Alzheimer's disease." (PMID 17854491, 2007). "These technologies, including whole-exome sequencing (WES) and whole-genome sequencing (WGS), have facilitated the identification of pathogenic mutations in genes such as APP, PSEN1, and PSEN2 in Alzheimer’s disease (AD), as well as LRRK2, SNCA, and PINK1 in Parkinson’s disease (PD)." (PMID 40076852, 2025). "Due to mutations in APP and genetic risk genes, such as PSEN1 and PSEN2 which alter amyloid concentrations, patients with DS are more prone to develop Alzheimer’s disease at an earlier age (30–60 years) than those with late-onset Alzheimer’s disease (≥65 years)." (PMID 37238612, 2023). "The associations of non‐pathogenic variants of APP, PSEN1, and PSEN2 with Alzheimer's disease (AD) remain unclear." (PMID 36217304, 2023). "This early onset of the inherited form of Alzheimer’s disease has been linked to a lack of PSEN-2 function caused by mutation, which leads to incomplete digestion of the amyloid peptide and may contribute to increased vulnerability in the brain." (PMID 36678510, 2022). "Interestingly, AKT1, MAPK8, BCL2L1, FOXO3, and CTNNB1 were not only significantly associated with pathogenic genes (APP, MAPT, and PSEN2) but also with longevity in Alzheimer’s Disease." (PMID 36620771, 2022).
Alzheimer disease (continued). "Finally, dysregulation of Alzheimer's disease-associated genes including amyloid protein precursor, α-secretase, β-secretase, presenilin 1, presenilin 2, and tau protein occurs in a course of postischemic neurodegeneration." (PMID 34527172, 2021). "It provides Alzheimer's disease-linked gene changes of the amyloid protein precursor, α-secretase, β-secretase, presenilin 1, presenilin 2, and tau protein in experimental post-ischemic injury in the CA1 and CA3 areas of the hippocampus and medial temporal cortex." (PMID 33679381, 2021). "The Dominantly Inherited Alzheimer Network (DIAN) is an international observational study of APP, PSEN1, and PSEN2 mutation carriers with the goal of determining the sequence of changes in presymptomatic mutation carriers who are destined to develop Alzheimer disease." (PMID 30045758, 2018). "Among the genes, PSEN2 (presenilin-2) is extremely correlated with Alzheimer’s disease (AD) risk." (PMID 22761725, 2012). "The evidence that mutations in PSEN1/PSEN2 that cause Familial Alzheimer's disease are loss of function mutants, and that loss of PSEN1/PSEN2 function causes neurodegeneration in mice, supports this hypothesis." (PMID 20661273, 2010). "PRESENILIN 2 (PSEN2) is one of the genes mutated in early onset familial Alzheimer’s disease (EOfAD)." (PMID 32658922, 2020). "Furthermore, the identification of Psen2 (presenillin 2), a gene implicated in Alzheimer's disease, as candidate hub gene is interesting because genes implicated in Alzheimer's have been reported to affect cholesterol or lipoprotein function and have also been implicated in atherosclerosis." (PMID 23193398, 2012). "Mutations in amyloid-beta precursor protein (APP), presenilin 1 and 2 (PSEN1, PSEN2) are known to cause early onset (<60 years) familial Alzheimer disease (AD)." (PMID 22312439, 2012). "Alzheimer’s disease is strongly linked to rare mutations in APP, PSEN1, and PSEN2 genes, while the APOE allele represents the strongest genetic risk factor for sporadic AD." (PMID 41143248, 2025). "Our analysis of FAD mutations in PSEN1, PSEN2, and APP has focused exclusively on neurons, a key brain cell type affected in Alzheimer’s disease." (PMID 39754192, 2025). "Alzheimer’s disease is linked to several genetic mutations, including amyloid precursor protein (APP) and presenilin genes (PSEN1 and PSEN2) mutations that have been found to be the most common, leading to early-onset Alzheimer’s disease." (PMID 41007636, 2025). "We investigated mutations linked to early-onset Alzheimer’s disease (EOAD), particularly in the APP, PSEN1, and PSEN2 genes, which affect amyloid-beta production and neuronal integrity." (PMID 40725212, 2025). "Background/Objectives: Background: Early-onset Alzheimer’s disease (EOAD) is primarily inherited in an autosomal dominant pattern, with mutations in the APP, PSEN1, and PSEN2 genes being central contributors." (PMID 40149496, 2025). "Familial early-onset Alzheimer's disease (EOAD) is a rare form of dementia often caused by autosomal dominant mutations in APP, PSEN1, or PSEN2." (PMID 40575115, 2025). "Mutations that lead to the development of early-onset Alzheimer’s disease are found within the APP (amyloid precursor protein), PSEN1 (presenilin 1), and PSEN2 (presenilin 2) genes, the products of which regulate the production of Aβ." (PMID 40869138, 2025). "ADAD accounts for approximately 1% of Alzheimer’s disease (AD) cases and is caused by autosomal dominant mutations in the Amyloid Beta Precursor Protein (APP), Presenilin 1 (PSEN1), or Presenilin 2 (PSEN2) genes." (PMID 39828719, 2025). "Familial Alzheimer’s Disease (FAD) is primarily caused by mutations in the APP, PSEN1, and PSEN2 genes, which encode proteins critical to Aβ generation and clearance." (PMID 40529145, 2025). "Familial Alzheimer’s disease (fAD) is a rare, inherited, autosomal dominant form of AD caused by mutations in PSEN1, PSEN2 and APP." (PMID 40542358, 2025).